MEF2D (myocyte enhancer factor 2D)
Diseases named in the same sentence as MEF2D in open-access papers (continued):
Sharing a sentence is not in itself a finding about the gene and the disease.
tumor (45 papers, 2013 to 2026). "For instance, abnormal MEF2D activity is associated with treatment resistance, invasiveness, and tumor progression in some cardiac and muscular sarcomas." (PMID 41155227, 2025). "MEF2D is deregulated in different neoplasms and is associated with tumor progression and poor prognoses." (PMID 38791246, 2024). "In liver cancer, overexpression of MEF2D is associated with tumor cell proliferation, invasion and metastasis, and immunosuppression." (PMID 39744125, 2024). "Increased cell proliferation and tumor formation resulting from MEF2D knockout prompted us to investigate whether the loss of MEF2D function led to a loss of contact inhibition." (PMID 38791246, 2024). "MEF2D encodes the myocyte enhancer factor 2D, a transcription factor that was initially found to be associated with muscle cell differentiation but which also affects tumor development and progression." (PMID 29029385, 2017). "We show that RNF39 is transcriptionally activated by MEF2D and enhances tumour cell proliferation and invasion by suppressing RINT1 accumulation, thereby attenuating UPR activation and preventing ER stress‐induced apoptosis." (PMID 41457280, 2026). "This transcriptional link integrates RNF39 into a broader oncogenic regulatory network, where MEF2D acts as a nodal point coordinating transcriptional and post‐translational pathways that support tumour cell survival." (PMID 41457280, 2026). "MEF2D, a member of the myocyte enhancer factor family, is aberrantly overexpressed in multiple malignancies, facilitating tumour proliferation, invasion, and drug resistance through the regulation of downstream genes." (PMID 41158124, 2025). "MEF2D, a master regulator of transcriptional reprogramming in cancer-related genes, has been reported to be overexpressed in HCC and is associated with tumor cell proliferation, invasion, and migration." (PMID 39744125, 2024). "In summary, we reported a novel molecular signaling pathway that the acidic tumor microenvironment promotes PC progression through the miR-451a/MEF2D axis, which provides a novel therapeutic target for PC." (PMID 35069734, 2022). "MEF2D promotes tumor growth, metastasis and angiogenesis, affects tumor cells and even the tumor microenvironment, increases PD-L1 expression in HCC cells, and suppresses CD8+ T cell-mediated antitumor immunity." (PMID 36176401, 2022). "MEF2B, MEF2C, and MEF2D are predominantly involved in tumor proliferation, migration, and invasion and in tumor immunity." (PMID 33863999, 2021). "Forced overexpression of MYOG or MEF2D suppresses RMS tumor growth and induces skeletal muscle differentiation." (PMID 32060262, 2020). "Myocyte enhancer factor 2D (MEF2D) has also been proven to play a central role in tumour angiogenesis." (PMID 31835751, 2019). "Factors secreted by RENCA macrobeads significantly up-regulated the activity of the MEF2 transcription factor as well as altered the transcription of MEF2b and MEF2d isoforms in targeted tumor cells." (PMID 30514247, 2018). "The regulation of MEF2D is still controversial, with studies publishing both oncogenic and tumor suppressive capacities for this isoform." (PMID 30514247, 2018). "Increasing evidences indicate that MEF2C and MEF2D both act as tumor-promoting or -suppressing proteins dependent on the type of cancer." (PMID 29340119, 2017). "A surprising aspect of this study was the dramatic effect of MEF2D on cell motility, migration, anchorage independent growth and tumor growth in vivo." (PMID 24279793, 2013). "We have confirmed the inhibition of tumorigenicity by MEF2D in a tumor xenograft model, with a complete regression of tumor growth." (PMID 24279793, 2013). "The results show that MEF2D is enriched in CDKN2A-expressing tumor epithelia and can target CDKN2A." (PMID 38888512, 2024). "MEF2D may, thus, be a putative tumor suppressor, acting through selective gene regulatory programs that have clinical and therapeutic significance." (PMID 38791246, 2024).
tumor (continued). "According to previous research, MEF2D is abundant in many different tumour tissues." (PMID 34109727, 2021). "We recently reported that in CD4+CD25+Foxp3+ T-regulatory (Treg) cells, Mef2d is required for the acquisition of an effector Treg (eTreg) phenotype and for the activation of an epigenetic program that suppresses the anti-tumor immune responses of conventional T and B cells." (PMID 34290714, 2021). "Furthermore, miR-361 also suppressed the expression of multiple prometastatic genes and tumor microenvironment-related genes, including MEF2D, ROCK1, WNT7A, VEGF-A, PDE4B, and KPNA4." (PMID 31287002, 2019). "In contrast, overexpression of MEF2D led to a complete block of tumor growth." (PMID 24279793, 2013). "Our work suggests that reactivating MEF2D in RMS cells is an attractive therapeutic target for inhibiting the tumor growth of these cells which may provide new insight into treatment of this pediatric cancer." (PMID 24279793, 2013). "Our results are highly suggestive that restoring MEF2D in RMS cells may effectively impede tumor growth and dissemination." (PMID 24279793, 2013). "Thus, MEF2D‐mediated activation of the integrin‐FAK signaling is broadly observed across multiple tumor types, which may serve as valuable prognostic biomarkers across various human cancers." (PMID 37828611, 2023). "In addition, we predicted and confirmed a novel target of miR-451a, MEF2D, representing an oncogenic protein that could regulate tumor suppression in PC." (PMID 35069734, 2022). "MEF2D can enhance the expression of the VEGF gene in tumor cells, thereby promoting angiogenesis and inducing abnormal proliferation of tumor cells." (PMID 40013141, 2025). "Although MEF2A and MEF2D have been linked to differentiation of muscle and cardiac cells, in the absence of regular growth signals, tumor cells may proliferate due to dysregulation of the MEF2 family, which can cause unchecked growth and aberrant metabolic adaption." (PMID 41155227, 2025). "Hsa-miR-329-3p inhibits lysine-specific dymethylase 1A (KDM1A), which increases the methylation of Myocyte Enhancer Factor 2D (MEF2D), reducing the expression of PD-L1 and blocking tumor growth, as demonstrated in a xenograft model of HCC." (PMID 36230554, 2022). "In colorectal cancer tissues, MEF2D is positively correlated with CD31‐positive microvascular density and promote tumour angiogenesis in vitro and in vivo, resulting in induction of expression of proangiogenic cytokines." (PMID 34109727, 2021). "When validating these potential targets in patients samples, we found that three targets named CSRNP1, MEF2D and EPAS1 are significantly up-regulated in tumor tissues when compared with normal tissues." (PMID 30696880, 2019). "Results showed that CSRNP1, MEF2D and EPAS1 are significantly up-regulated in tumor tissues compared with normal tissues." (PMID 30696880, 2019). "Using online algorithms, we were able to predict potential miR-361 target genes involved in cancer metastasis, such as MEF2D, ROCK1 and WNT7A, and the tumor microenvironment, including KPNA4, PDE4B and VEGF-A." (PMID 31287002, 2019). "The development and survival of tumor cells depend on the involvement of the MEF2 (Myocyte Enhancer Factor 2) family, which includes MEF2A, MEF2B, and MEF2D; these TFs are involved in signaling pathways that regulate cellular homeostasis and metabolic adaptation." (PMID 41155227, 2025). "Though miR-421 has been identified to target multiple mRNAs to alter tumor progression, such as FOXO4, MEF2D, and MTA1, whether miR-421 can target PDE7B remains to be uncovered." (PMID 33817314, 2021). "Mechanistically, miR-329-3p inhibits tumor cellular immunosuppression and reinforces the response of tumor cells to T cell-induced cytotoxic effect by targeting KDM1A mRNA and downregulating its expression, which contributed to MEF2D demethylation and activation of PD-L1 expression." (PMID 34307695, 2021).
tumor (continued). "We have shown here that MEF2D expression is affected at the level of both RNA and protein in four independent RMS cell lines representing both common subtypes of RMS and in primary tumor cells from a mouse model of ERMS." (PMID 24279793, 2013).
cancer (29 papers, 2013 to 2025). A tumor composed of atypical neoplastic, often pleomorphic cells that invade other tissues. "This discrepancy between studies indicates that the cancer driver function of MEF2D is cell-type-specific and context-dependent." (PMID 38791246, 2024). "Immunohistochemical staining was used to detect MEF2D expression levels in cancer and adjacent tissues." (PMID 37653017, 2023). "Growing evidence suggested that miR-335 inhibited cancer cell viability and induced cell cycle arrest by inhibiting the expression of myocyte enhancer factor 2D (MEF2D)." (PMID 34944491, 2021). "Although Mef2c is expressed at very low levels in Tregs, Mef2c-/- mice rapidly reject heart allografts and restrain cancer growth in syngeneic models, similarly to Mef2d-/- mice." (PMID 34290714, 2021). "MEF2D is highly expressed in various malignancies and participating in biological functions of cancer cells." (PMID 34109727, 2021). "Long-coding RNAs (lncR-D63785) are emerging trends in cancer implications, and it was revealed that lncR-D63785 expression inversely correlated with miR-422a which can downregulate MEF-2D and drug sensitivity in gastric carcinoma." (PMID 31105874, 2019). "The MEF2D levels were also decreased in patients with LCC or SCLC as compared with non-cancer tissues." (PMID 28340574, 2017). "While targeted knockdown of MEF2D gene via siRNA significantly impaired the capacity of cancer cell differentiation, proliferation or movement." (PMID 28340574, 2017). "MEF2D is overexpressed in colorectal cancer tissues and it promotes cancer cell invasion and metastasis." (PMID 29340119, 2017). "In patients with NSCLC, the expressions of MEF2A and MEF2D were significantly higher, compared with non-cancer tissues (p < 0.01 and 0.001, respectively)." (PMID 28340574, 2017). "The relative lower phosphorylation level of S444 in QGY and Hep3B than L02 suggesting MEF2D is activated in cancer cell lines." (PMID 28883432, 2017). "We previously found that the transcription factors MEF2D and GATA3, as well as the histone deacetylases HDAC3 and HDAC9, regulate BRM expression in BRM-deficient cancer cell lines." (PMID 24913006, 2014). "This difference could be due to metastatic stage‐specific or cancer type‐specific functions of MEF2D." (PMID 37828611, 2023). "Many studies manifest MEF2D participating in tumorigenesis and cancer progression." (PMID 34109727, 2021). "Aberrant MEF2D expression and phosphorylation affect cancer cell normal function." (PMID 34109727, 2021). "In Treg cells, Mef2d is required to sustain and integrate the Foxp3 transcriptional repertoire; Mef2d deletion in Foxp3+ cells impairs the acquisition of an eTreg phenotype and leads to an increase in anti-cancer immunity and transplant rejection." (PMID 34290714, 2021). "Collectively, expression of MEF2D is vitally important to cancer pathogenesis and progression." (PMID 34109727, 2021). "Briefly, inflammatory conditions led to increased MEF2D expression, which might further contribute to the development of malignancy through influencing cancer microenvironment and cell bio-behaviors." (PMID 28340574, 2017). "Given the critical roles of MEF2 in regulation of inflammatory responses, up-regulation of MEF2D might lead to remodeling of cancer microenvironment through lymphocytes recruitment or mediators production during inflammatory condition." (PMID 28340574, 2017). "Consistent with our previous study, we provide further evidence that inflammatory conditions might contribute to remodeling of the cancer microenvironment through up-regulating MEF2D expression." (PMID 28340574, 2017). "Consistently, MEF2D positively correlated with these highly expressed integrins in HCC and other cancer types." (PMID 37828611, 2023). "MEF2D, a member of the MEF2 family, is a crucial developmental factor, showing an essential role in the tumorigenesis of various malignant tumor cells." (PMID 35069734, 2022).
cancer (continued). "Together, these results suggest that SIK2 inhibitors enhance the vulnerability of cancer cells to olaparib, not only by inhibiting PARP enzyme activity but also by blocking the class-IIa HDAC/MEF2D–mediated DNA repair function." (PMID 35642638, 2022). "The effects of miR-30a on the invasion of CC due to its inverse correlation with myocyte enhancer factor 2D (MEF2D), one member of the MEF2 family that is involved in the progression of various cancers." (PMID 30833362, 2019). "Along with Robo1, other molecules like receptor protein tyrosine phosphatase alpha (RPTPα), myocyte enhancer factor 2D (MEF2D), and runt-related transcription factor 2 (RUNX2) are post-transcriptional target molecules of miR-218, which are known to induce cancer metastasis like MACC1." (PMID 27462788, 2016).
neurodegenerative disease (5 papers, 2015 to 2024). A disorder of the central nervous system characterized by gradual and progressive loss of neural tissue and neurologic function. "Such proteins that are degraded via CMA include those associated with neurodegenerative diseases such as MEF2D, Htt as well as the glycolytic enzyme GAPDH." (PMID 25637286, 2015). "Furthermore, leucine-rich repeat kinase 2 (LRRK2) and myocyte enhancer factor 2D (MEF2D) have been identified as typical CMA substrates in neurodegenerative diseases." (PMID 38472355, 2024). "Hyperactivity of Cdk5/p25 contributes to the pathologic progression of several degenerative diseases by phosphorylation different relevant substrates, e.g., tau, neurofilament proteins, and β-amyloid precursor protein related to AD, MEF2D, synuclein, Parkin, and Prx2 related to PD." (PMID 29910724, 2018).
cardiovascular disease (2 papers, 2021 to 2022). "Of these genes MEF2D is most widely studied in cardiovascular disease, since the family of MEF2 transcription factors is regulators of skeletal, cardiac and smooth muscle cell development." (PMID 34895303, 2021). "In the top 20 pathways, the cGMP-PKG signalling pathway and viral carcinogenesis were the common signalling pathways regulated by Mef2d, and the cGMP-PKG signaling pathway was selected for further research due to its noticeable function in T2D-related cardiovascular diseases." (PMID 35794619, 2022).
infection (1 paper, 2015). The state of being infected such as from the introduction of a foreign agent such as serum, vaccine, antigenic substance or organism. "Infection of rat skeletal muscle with Ad-PIMT EGFP resulted in a robust decrease in the transcript levels of GLUT4, MEF-2A and MEF-2D." (PMID 26468734, 2015). "Consistent with the data from cultured cells, infection with Ad-PIMT Ser298Asp but not Ad-PIMT Ser298Ala suppressed GLUT4, MEF2A, MEF2D expression while up-regulating PGC1-α, HDAC5 and MEF2C expression in the rat skeletal muscle tissue." (PMID 26468734, 2015). "Importantly, infection with Ad-PIMT or Ad-PIMT Ser298Asp but not PIMT Ser298Ala resulted in a dramatic reduction of MEF2A and MEF2D expression in L6 myotubes." (PMID 26468734, 2015).
neurological disorders (1 paper, 2021). "MEF2D is a transcription factor that plays a critical role in dopaminergic neuronal survival in neurological disorders, possibly in AD." (PMID 34276354, 2021).
MEF2D also shares sentences with these, for which no sentence is quoted: Alzheimer disease (2 papers); autoimmune disease (2); cognitive disorder (2); multiple myeloma (2); adenocarcinoma of the breast (1); Anxiety (1); astrocytoma of the brain (1); B-cell precursor acute lymphoblastic leukemia (1); bacterial infection (1); cervical cancer (1); dementia (1); depression (1); diffuse large B-cell lymphoma (1); dissection (1); Ewing sarcoma (1); Headache (1); Intellectual disability (1); liposarcoma (1); liver fibrosis (1); mental illnesses (1); multiple sclerosis (1); muscular dystrophies (1); myocardial infarction (1); neuroblastoma (1); neurodevelopmental disorder (1); Parkinson’s (1); psoriasis (1); rheumatoid arthritis (1); schizophrenia (1); thyroid carcinomas (1).
A further 1 disease shares a sentence with MEF2D in 1 paper.